IDO1 (indoleamine 2,3-dioxygenase 1)
Diseases named in the same sentence as IDO1 in open-access papers (continued):
Sharing a sentence is not in itself a finding about the gene and the disease.
parasite infection (9 papers, 2016 to 2026). "Although little is known about the role of IDO1 in parasitic infections, it could play a regulatory role in preventing an exacerbated immune response." (PMID 39119291, 2024). "Among these pathways, IDO1 has been shown to modulate the T in response to the parasitic infection." (PMID 30248353, 2018). "Moreover, TgIST-independent (STAT1-independent) expression of IDO1 fully recovered the IFN-γ-induced growth inhibition by TgIST-sufficient parasite infection." (PMID 30283439, 2018). "Thus, we conclude externally supplemented tryptophan in presence of IFN-γ augmented cellular IDO1 which negatively regulated activity of both AKT and β-catenin to prevent parasite infection (lane 8–10, first panel)." (PMID 30770800, 2019). "However, an increased kynurenine/tryptophan (KYN/TRP) ratio in children with parasitic infection may indicate the possibility of other cytokine induced IDO-1 activation, especially IFN-γ, which has not been quantified in this study." (PMID 34539633, 2021).
rectal cancer (9 papers, 2011 to 2025). A primary or metastatic malignant neoplasm that affects the rectum. "IDO1 was associated with G0/G1 phase arrest, and the IDO1 inhibitor 1-L-MT caused G2/M cell cycle block and prevented mitosis in rectal cancer cells." (PMID 36233312, 2022). "In the present de novo meta-analysis study, we found three genes: CXCL10, IDO1 and AKR1C3 associated to chemo-resistance in rectal cancer patients." (PMID 26359356, 2015). "The stereoisomer of 1-D-MT, 1-L-MT was recently reported to suppress the IFN-γ-induced expression of IDO1 in mouse rectal carcinoma cells." (PMID 21625531, 2011).
AIDS (8 papers, 2013 to 2023). A syndrome resulting from the acquired deficiency of cellular immunity caused by the human immunodeficiency virus (HIV). "Progressive HIV-infection is characterized by chronic inflammation and IDO-1 activation, and increased KT-ratio has been associated with non-AIDS defining morbidity in HIV-infected US subjects on suppressive ART40." (PMID 29712976, 2018).
epilepsy (8 papers, 2014 to 2026). A brain disorder characterized by episodes of abnormally increased neuronal discharge resulting in transient episodes of sensory or motor neurological dysfunction, or psychic dysfunction. "The frequency of SRSs was lower and the duration of SRSs was shorter in the IDO1-deficient pilocarpine-induced epilepsy group than in the WT pilocarpine-induced epilepsy group." (PMID 33679331, 2021). "To further explore the mechanisms of IDO1 in epilepsy, we evaluated the effects of IDO1 deficiency on neuronal loss, KYN metabolite levels, the inflammatory response, and oxidative stress in epileptic mice." (PMID 33679331, 2021). "IDO1 deficiency suppresses seizures and attenuates neuronal loss in a lithium-pilocarpine-induced epilepsy model." (PMID 33679331, 2021). "Conversely, our study revealed that IDO1 deficiency suppressed seizures in the lithium-pilocarpine model of epilepsy." (PMID 33679331, 2021). "As shown in a previous study, IDO1 contributes to epilepsy-associated depression-like behavior in chronic temporal lobe epilepsy." (PMID 33679331, 2021). "Our previous research demonstrated that activation of IDO1 contributes to epilepsy-associated depressive-like behavior." (PMID 33679331, 2021). "In this study, we report that indoleamine 2,3-dioxygenase 1 (IDO1), a rate-limiting enzyme in tryptophan metabolism, plays a key role in epilepsy-associated depressive-like behavior." (PMID 24594021, 2014). "The upregulation of IDO1 subsequently increased the kynurenine/tryptophan ratio and decreased the serotonin/tryptophan ratio in the hippocampus, which contributed to epilepsy-associated depressive-like behavior." (PMID 24594021, 2014). "Brain IDO1 activity plays a key role in epileptic rats with epilepsy-associated depressive-like behavior." (PMID 24594021, 2014). "However, our results do not provide direct evidence of the underlying mechanism by which IDO1 in microglia regulates the development of epilepsy." (PMID 33679331, 2021). "Collectively, these results indicated that IDO1 might be associated with human epilepsy." (PMID 33679331, 2021). "Patients with epilepsy showed a significantly higher IDO level and KYN/TRP ratio (IDO1 activity) in the sera and CSF than controls." (PMID 33679331, 2021). "In this study, IDO1 levels and IDO1 activity were increased in both patients with epilepsy and epileptic mice." (PMID 33679331, 2021). "IDO1 activity was significantly higher in the sera and CSF of patients with epilepsy compared with controls, especially in patients with SE." (PMID 33679331, 2021). "More research should be conducted to clarify the detailed mechanisms of how IDO1 affects epilepsy in the future." (PMID 33679331, 2021). "Male C57BL/6 mice and IDO1 knockout (KO, IDO1−/−) mice were subjected to intraperitoneal injection of lithium and pilocarpine to induce epilepsy." (PMID 33679331, 2021). "To investigate the response of IDO1 to epilepsy, we first measured IDO levels and the KYN/TRP ratio in the sera and CSF of patients with epilepsy and controls." (PMID 33679331, 2021). "To further confirm that IDO1 levels are altered in epileptic mice, we established a lithium-pilocarpine-induced epilepsy model and assessed IDO1 levels and the KYN/TRP ratio in the serum and hippocampus at different time points." (PMID 33679331, 2021). "The levels of IDO1 and concentrations of TRP and KYN in patients with epilepsy and epileptic mice were evaluated by enzyme-linked immunosorbent assay (ELISA) and liquid chromatography-mass spectrometry (LC-MS), respectively." (PMID 33679331, 2021). "Then, we utilized IDO1−/− mice to assess the effect of IDO1 on seizures in a lithium-pilocarpine-induced epilepsy model." (PMID 33679331, 2021).
epilepsy (continued). "The researchers found that IDO-1 levels, KYN/TRP ratio and pro-inflammatory cytokine levels were elevated in the serum and hippocampus of mice with epilepsy in both the acute and chronic phases following status epilepticus (SE), and this was reversed in IDO-1 knockout mice." (PMID 36159806, 2022). "Our study demonstrates that IDO1 may be involved in the pathogenesis of epilepsy and has the potential to be a therapeutic target for epilepsy treatment." (PMID 33679331, 2021). "In summary, IDO1 is promptly induced in response to epilepsy." (PMID 33679331, 2021). "To further explore whether IDO1 could affect epilepsy, we established a lithium-pilocarpine-induced epilepsy model in IDO1−/− mice and WT mice." (PMID 33679331, 2021). "The activation of IDO1 could alter brain TRY metabolism, which contributes to epilepsy-associated depressive-like behavior in rats with chronic TLE." (PMID 24594021, 2014). "Furthermore, IDO1 has been suggested to play a role in the pathogenesis of epilepsy." (PMID 40150625, 2025). "Therefore, in this study, we explored the role of IDO1 in epilepsy." (PMID 33679331, 2021). "We explored whether IDO1 would affect seizures in the lithium-pilocarpine-induced epilepsy model." (PMID 33679331, 2021). "Therefore, the elevation of IDO1 levels in microglia that produce QUIN might be an important factor in the pathogenesis of epilepsy." (PMID 33679331, 2021). "Thus, we hypothesized that IDO1 might mediate neurotoxic KYN metabolites to affect the pathogenesis of epilepsy." (PMID 33679331, 2021). "Therefore, our results suggest that IDO1 might be involved in the development of epilepsy." (PMID 33679331, 2021). "We further evaluated the changes in IDO1 levels and the KYN/TRP ratio using the lithium-pilocarpine-induced animal model, which is a classic model of epilepsy." (PMID 33679331, 2021). "First, we measured IDO1 levels and the KYN/TRP ratio in patients with epilepsy and an epileptic mouse model." (PMID 33679331, 2021). "IDO1 was not significantly different between the CP with epilepsy, CP without epilepsy, and healthy control groups (p = 0.110)." (PMID 40150625, 2025). "Indeed, IDO1 activation increases KYN derivatives, such as QUIN, a glutamate receptor agonist with neuroexcitatory and neurotoxic effects that induce epilepsy." (PMID 24594021, 2014). "Although we were unable to compare hippocampal IDO1 levels and the KYN/TRP ratio between patients with epilepsy and controls due to practical and ethical limitations, these findings provide evidence that IDO1 levels and the KYN/TRP ratio might be associated with the severity of behavioral seizures." (PMID 33679331, 2021).
gastrointestinal stromal tumor (8 papers, 2014 to 2024). "The therapeutic effect of imatinib, a tyrosine kinase inhibitor, in gastrointestinal stromal tumors (GIST) is also associated with downregulation of IDO1 expression, which, in turn, is driven by the oncogenic tyrosine-protein kinase KIT signaling." (PMID 34201791, 2021). "In addition, a recent study suggests that IDO1 is also driven by oncogenic KIT signaling in gastrointestinal stromal tumors (GIST)." (PMID 25628622, 2014).
neuroblastoma (8 papers, 2011 to 2022). Neuroblastoma (NB) is the most common solid, extracranial childhood tumor. "More recently, increased levels of KYNA and transcripts encoding IDO1 were also observed in primary neurons and neuroblastoma cells following IFN-γ treatment." (PMID 21982155, 2011). "In previous studies, exposure of several cultured human malignant glioma cell lines, primary neurons, and a neuroblastoma cell line to IFNγ reduced TRP levels in culture medium accompanied by increased IDO1 expression and KYN production." (PMID 32117235, 2020). "Similarly, other investigators showed that a variety of cancer cell types including, ovarian, and neuroblastoma and GBM cell lines over-expressed the IDO-1 enzyme, either constitutively or following IFN-γ stimulation when compared to normal cells." (PMID 25415278, 2014).
osteosarcoma (8 papers, 2019 to 2024). A usually aggressive malignant bone-forming mesenchymal neoplasm, predominantly affecting adolescents and young adults. "Given the fact that IDO1 is highly expressed on Ewing sarcoma cells and has been associated with worse outcome in osteosarcoma, among other cancers 160, 161, combining such IDO inhibitors with immunotherapy may provide significant therapeutic benefit for those patients." (PMID 36168619, 2022). "Correlation between IDO1 expression and laboratory test indexes in patients with osteosarcoma." (PMID 37284323, 2023). "Therefore, although we did not evaluate IDO1 expression in osteosarcoma, there may be crosstalk between PAK4 and IDO1, which could represent a novel therapeutic target in human cancers." (PMID 39273017, 2024).
cervical squamous cell carcinoma (7 papers, 2018 to 2025). A squamous cell carcinoma arising from the cervical epithelium. "In cervical squamous cell carcinoma, DCs express immunosuppressive molecules such as indoleamine 2,3-dioxygenase 1 (IDO1) and galectin-9 (LGALS9), while exhibiting low PD-L1 expression, revealing spatially heterogeneous mechanisms of immune suppression." (PMID 41050070, 2025). "The data showed a significant increase in IDO1, CXCL1, and CXCL8 mRNA expression in cervical squamous cell carcinoma and endocervical adenocarcinoma (CECS)." (PMID 37626777, 2023).
chlamydial infection (7 papers, 2014 to 2024). "A key mechanism of IFNγ expression in chlamydial infections and disease is the conversion of tryptophan to kynurenine utilising IDO1/2 through the NAD biosynthesis pathway (Team, R.C, 2018)." (PMID 39600869, 2024). "The IFNγ-induced enzyme, indoleamine-2,3-dioxygenase-1 (IDO1), catabolizes tryptophan into kynurenine, and is proposed to be the primary mediator of the IFNγ-induced protective response against chlamydial infection." (PMID 29855501, 2018). "Therefore, induction of the host tryptophan catabolizing enzyme, indoleamine-2,3-dioxgenase-1 (IDO1), by interferon gamma (IFNγ) is one of the primary protective responses against chlamydial infection." (PMID 29855501, 2018). "In this context interferon gamma (IFNγ) is the major host protective cytokine against chlamydial infections because it induces the expression of the host enzyme, indoleamine 2,3-dioxygenase 1, that degrades tryptophan, thereby restricting bacterial replication." (PMID 27658027, 2016). "Despite the low number of participants, our results suggest that indeed the chlamydial infection did trigger an IFN-γ response and subsequent IDO1 production, which degraded pools of vaginal tryptophan to kynurenine." (PMID 29404279, 2018).
chronic kidney disease (7 papers, 2018 to 2026). Impairment of the renal function secondary to chronic kidney damage persisting for three or more months. "Indoleamine 2,3-dioxygenase-1 (IDO-1), a rate-limiting enzyme of kynurenine biogenesis, was proved to be a novel therapeutic target for post-vascular injury thrombosis in chronic kidney disease (CKD)." (PMID 40147625, 2026). "It should be emphasized that the chronic kidney disease secondary to T2DM is associated with oxidative stress and inflammation which in turn induces IDO1." (PMID 39902076, 2024). "In a nephrotoxic serum nephritis mouse model, IDO enzymatic inhibition using 1-MT (-d or -l isomer) exacerbated proteinuria and end-stage renal disease signifying a protective role for IDO, although whether this can be accredited to IDO1 or IDO2 was not determined." (PMID 31555267, 2019).
coronary artery disease (7 papers, 2019 to 2024). "It is shown that IDO1 activity has an inverse association with ischemic heart disease and therefore it has been introduced as a potential therapeutic target for this disease." (PMID 36879035, 2023). "They concluded that the life-long increased plasma IDO1 was inversely associated with risk of developing ischemic heart disease." (PMID 35211110, 2021). "The importance of IDO enzymes in prognosis of cardiovascular diseases was supported by Li’s work, where a Mendelian Randomization was used to obtain unconfounded estimates of the association of IDO1 with ischemic heart disease, ischemic stroke and their risk factors." (PMID 35211110, 2021). "Moreover, several reports suggest that the cytokine interferon-gamma, which is released during the cell-mediated immune responses that take place in coronary heart diseases, induces IDO-1 activity." (PMID 37616231, 2023).
graft versus host disease (7 papers, 2017 to 2023). An immune system disorder that occurs after allogeneic hematopoietic stem cell transplant and is a reaction of donor immune cells against host tissues. "IDO-1 is a potent regulatory mediator mostly associated with myeloid and mesenchymal stromal cells with implications in feto-maternal tolerance, tumor immune escape, autoimmunity and alloimmune responses such as graft-versus-host disease." (PMID 37828996, 2023). "Several previous studies have demonstrated the protective role of IDO1 in graft-versus-host disease (GVHD)." (PMID 35281025, 2022). "On the other hand, induction of IDO-1 reduced colon injury and ameliorated lethality in graft-versus-host disease in mice." (PMID 31181125, 2019). "The protective effects of IDO1 were confirmed in a mouse model of graft versus host disease." (PMID 33413597, 2021).
Huntington disease (7 papers, 2018 to 2022). Huntington disease (HD) is a rare neurodegenerative disorder of the central nervous system characterized by unwanted choreatic movements, behavioral and psychiatric disturbances and dementia. "Published literature has shown that IDO1 activity is increased in the blood of Huntington’s disease patients." (PMID 33679331, 2021). "Increased KYN content and IDO1 activity have been detected in the blood of Huntington’s disease patients." (PMID 33679331, 2021).
Lewis lung carcinoma (7 papers, 2013 to 2026). "However, using IDO1-deficient mice, host IDO1 has been found to play a role in promoting tumor growth, MDSC accumulation and expression of PD-1 by CD8+ T cells in a model of Lewis lung carcinoma." (PMID 39211039, 2024). "A study reported that IDO1 blockage could overcome radiation-induced “Rebound Immune Suppression” in the tumor microenvironment and sensitized Lewis lung carcinoma (LLC) tumors to hypo-fractionated RT." (PMID 36824664, 2023). "Using mouse Lewis lung carcinoma (LLC1) cells, knocking down IDO1 has been shown to reduce cell growth in vitro." (PMID 37985999, 2023). "STING agonists also induced tolerogenic responses that promoted Lewis Lung Carcinoma (LLC) growth in mice by stimulating IDO activity in inflamed lymph nodes draining sites of tumor growth, though cGAS was not essential to induce IDO1 in the LLC model." (PMID 32625215, 2020).
lung diseases (7 papers, 2014 to 2023). "These genes include the long non-coding gene LINC01278 and some other genes known to be involved in the interferon network but lacking understanding of their role in pulmonary diseases, such as IDO1 and BTN3A2." (PMID 36203777, 2022).
malaria (7 papers, 2011 to 2026). Malaria is a serious and sometimes fatal disease caused by a parasite that commonly infects a certain type of mosquito which feeds on humans. "Previous studies that evaluated the role of the tryptophan degradation pathway in malaria have consistently shown that the activity of IDO1 is deleterious, and that it is associated with the development of disease complications (cerebral malaria, severe disease, hypotension, among others)." (PMID 32256470, 2020). "•Malaria induce immunosuppressive effect manifested with strong induction of IDO1." (PMID 30248353, 2018). "The mechanisms of immunosuppression that we have shown here could be harnessed to improve current malaria vaccines by targeting specific molecules such as the IDO1, to overcome parasite immune evasion." (PMID 30248353, 2018). "Recent findings suggest that IDO1-catabolized tryptophan-derivedmetabolites activate the aryl hydrocarbon receptor (AhR) and promoteregulatory T cells in P. vivax infection, providing further insights into the functionalroles of tryptophan metabolism in malaria." (PMID 41180073, 2025). "Additionally, DCs of humans inflicted with malaria mediated strong immunosuppression through the induction of Indoleamine 2,3-Dioxygenase 1(IDO1) and Lymphocyte Activation Gene 3 (LAG3), which attenuates inflammatory response by decreasing class II antigen presentation." (PMID 34414129, 2021). "Pc infection resulted in increased expression of Ido1 and decreased expression of downstream kynurenine pathway genes in the liver, suggesting that these metabolites may be produced in other tissues during malaria." (PMID 33021470, 2020).
malignant glioma (7 papers, 2014 to 2024). A grade III or grade IV glioma arising from the central nervous system. "It is also known that IDO-1 activity in human glial and malignant glioma cell lines is increased by IFN-γ." (PMID 25415278, 2014). "Most important of all, IDO1 inhibitor could benefit a subset of patients with recurrent malignant glioma in a phase 1 study." (PMID 33928021, 2021). "In addition to the rate-limiting enzyme indoleamine-2,3-dioxygenase-1 (IDO1), tryptophan catabolism via tryptophan-2,3-dioxygenase (TDO2) is a feature of many tumors, particularly malignant gliomas." (PMID 32477324, 2020).